SULT1B1 (sulfotransferase family 1B member 1)
Description:
Sulfotransferase that utilizes 3'-phospho-5'-adenylyl sulfate (PAPS) as sulfonate donor to catalyze the sulfate conjugation of dopamine, small phenols such as 1-naphthol and p-nitrophenol and thyroid hormones, including 3,3'-diiodothyronine, triidothyronine (T3) and reverse triiodothyronine (rT3). May play a role in gut microbiota-host metabolic interaction. O-sulfonates 4-ethylphenol (4-EP), a dietary tyrosine-derived metabolite produced by gut bacteria. The product 4-EPS crosses the blood-brain barrier and may negatively regulate oligodendrocyte maturation and myelination, affecting the functional connectivity of different brain regions associated with the limbic system.
Synonyms: ST1B1; ST1B2; SULT1B2
Tractability: Small molecule: a structure with a bound ligand is known; it has a high-quality binding pocket. PROTAC: its protein half-life has been measured.
Target class: Enzyme; Transferase
Gene: Protein-coding gene on chromosome 4 (69,721,167 to 69,787,961, reverse strand). Ensembl gene ENSG00000173597.
Subcellular location: Cytoplasm
Subcellular location (Human Protein Atlas): Golgi apparatus; Nucleoplasm
Pathways (Reactome):
Metabolism: Cytosolic sulfonation of small molecules
Gene Ontology:
Molecular function: aryl sulfotransferase activity; protein binding; sulfotransferase activity
Biological process: 3'-phosphoadenosine 5'-phosphosulfate metabolic process; epithelial cell differentiation; ethanol catabolic process; flavonoid metabolic process; phenol-containing compound metabolic process; sulfation; thyroid hormone metabolic process; xenobiotic metabolic process; biogenic amine metabolic process; sulfur compound metabolic process
Cellular component: cytoplasm; cytosol
Genetic constraint (gnomAD): Loss-of-function variants: 22 observed, 30.33 expected, observed/expected ratio (o/e) 0.73, 90% interval 0.52 to 1.04. The upper end of that interval is the gene's LOEUF score, 1.04, which puts it in group 4 of 6, group 1 being the genes least tolerant of losing a copy. Missense variants: 346 observed, 342.76 expected, observed/expected ratio (o/e) 1.01, 90% interval 0.92 to 1.1. Synonymous variants: 135 observed, 107.34 expected, observed/expected ratio (o/e) 1.26, 90% interval 1.09 to 1.45.
Homologues: Orthologues: chimpanzee SULT1B1 (98% identical), macaque SULT1B1 (96% identical), pig SULT1B1 (84% identical), dog SULT1B1 (84% identical), rat Sult1b1 (74% identical), mouse Sult1b1 (72% identical), zebrafish sult2st3 (34% identical), Drosophila melanogaster St3 (29% identical), Drosophila melanogaster St4 (28% identical), Drosophila melanogaster St1 (28% identical). Paralogues in human: SULT1E1 (55% identical), SULT1A2 (54% identical), SULT1A1 (53% identical), SULT1C4 (53% identical), SULT1A3 (53% identical), SULT1A4 (53% identical), SULT1C2 (52% identical), SULT1C3 (50% identical), SULT2A1 (37% identical), SULT2B1 (36% identical), SULT4A1 (32% identical), SULT6B1 (30% identical).
Diseases named in the same sentence as SULT1B1 in open-access papers:
SULT1B1 is named in the same sentence as 9 diseases in open-access papers, as found by Europe PMC text mining. Sharing a sentence is not in itself a finding about the gene and the disease. The quoted sentences say what the papers report.
cholangiocarcinoma (1 paper, 2025). A carcinoma that arises from the intrahepatic biliary tree (intrahepatic cholangiocarcinoma) or from the junction, or adjacent to the junction, of the right and left hepatic ducts (hilar cholangiocarcinoma). "In Cholangiocarcinoma, SULT1B1 is closely associated with tumor differentiation." (PMID 41383582, 2025).
colorectal cancer (1 paper, 2025). A primary or metastatic malignant neoplasm that affects the colon or rectum. "Regarding colorectal cancer, the suppression of SULT1B1 is closely linked to tissue dedifferentiation." (PMID 41383582, 2025).
inflammatory bowel disease (1 paper, 2022). A spectrum of small and large bowel inflammatory diseases of unknown etiology. "Some genes, for example SULT1B1 (OMIM 608436) and SULT1E1 (OMIM 600043), have been associated with HS and inflammatory bowel disease." (PMID 35203664, 2022).
Sepsis (1 paper, 2025). Sepsis is defined as life-threatening organ dysfunction caused by a dysregulated host response to infection. "For example, the genomic stability regulation of MYO10 may be associated with apoptosis resistance caused by mitochondrial damage in immune cells during sepsis, while the metabolic modification function of SULT1B1 may be involved in sepsis-related disorders of adrenocortical hormone metabolism." (PMID 41246299, 2025). "Literature on SULT1B1 involvement in sepsis-related adrenocortical hormone metabolic disorders shows: Recent studies have confirmed that ribosomal dysfunction and FcγR-mediated phagocytic abnormalities play critical roles in sepsis." (PMID 41246299, 2025). "The potential mechanisms of the four biomarkers (MYO10, SULT1B1, MKI67, CREB5) identified in this study in sepsis can be preliminarily interpreted through their known functions and related pathways." (PMID 41246299, 2025). "The RT-qPCR results showed the expression of MYO10, SULT1B1, MKI67, and CREB5 had significant differences between controls and sepsis samples (P < 0.05)." (PMID 41246299, 2025). "Secondary clustering and pseudotime analysis of monocytes showed that CREB5 and SULT1B1 tended to be stable in their five differentiation states after significant downregulation in early differentiation, suggesting that they may be involved in the progression of sepsis." (PMID 41246299, 2025). "This study identified 4 biomarkers, namely MYO10, SULT1B1, MKI67, and CREB5 and explored the pathogenesis of sepsis, providing new insights for potential treatment strategies by integrating transcriptomic data and single-cell analysis." (PMID 41246299, 2025). "This study obtained a total of 4 biomarkers (MYO10, SULT1B1, MKI67, and CREB5), and the analysis of nomogram showed that the biomarkers had good clinical predictive value to sepsis." (PMID 41246299, 2025). "In summary, these biomarkers may be involved in sepsis through mechanisms related to cell cycle regulation (MYO10, MKI67), metabolic reprogramming (SULT1B1), and inflammatory signal transduction (CREB5)." (PMID 41246299, 2025). "SULT1B1, a critical enzyme in sulfur metabolism and hormone modification, may affect common metabolic disorders in sepsis patients (such as non-thyroidal illness syndrome) by regulating thyroid hormone metabolism." (PMID 41246299, 2025).
tumor (6 papers, 2017 to 2025). "In vitro experiments have shown that the gene SULT1B1, which exhibits the highest accuracy in predicting tumor status, significantly inhibited the proliferation and metastasis." (PMID 41383582, 2025). "The CCK8 assay results demonstrated that the knockdown of SULT1B1 was capable of promoting the tumor cell proliferation of KYSE150 and KYSE410 cells." (PMID 41383582, 2025). "The ROC results indicated that among the six model CRGs, SULT1B1 exhibited the highest accuracy in predicting the tumor status." (PMID 41383582, 2025). "The collected data proposed that SULT1B1 might have a tumor-suppressing function in the progression of ESCC." (PMID 41383582, 2025). "Moreover, as one of the model CRGs, the tumor-suppressive role of SULT1B1 in ESCC was experimentally verified in vitro." (PMID 41383582, 2025). "Among the six model CRGs, SULT1B1 demonstrates the highest accuracy in predicting the tumor status." (PMID 41383582, 2025). "Additionally, our cell-based experiments demonstrated that SULT1B1 exerts a tumor-suppressing effect by modulating cell proliferation and migration." (PMID 41383582, 2025). "PTGR1, C1orf115, CRYL1, ALDOB, and SULT1B1 may be tumor suppressor genes involved in GC progression." (PMID 38737262, 2024). "Moreover, numerous studies conducted in recent years have revealed that SULT1B1 might exhibit tumor suppressive activity in a diverse range of cancers." (PMID 41383582, 2025). "Moreover, we have initially elucidated the tumor-suppressing function of SULT1B1 in ESCC." (PMID 41383582, 2025). "Sulfate conjugation by other SULT enzymes (SULT1A3, SULT1E1 and SULT1B1) may result in the activation or inactivation of anti-cancer drugs (e.g., raloxifene, sesamol, fulvestrant, and resveratrol), thereby affecting their anti-tumor effects." (PMID 28634336, 2017). "The activities of SULT1A1, SULT1B1, SULT1E1 and SULT2A1 in 9 of 10 samples showed a significant decrease in tumor tissues relative to matched pericarcinomatous tissues, whereas the activities of SULT1A3 in 7 of 10 samples increased." (PMID 28634336, 2017). "Thus, using probe substrates, we systematically measured the metabolic functions of SULT1A1, SULT1A3, SULT1B1, SULT1E1, and SULT2A1 in tumor S9 (tHLS9-pooled), pericarcinomatous S9 (nHLS9-pooled), and reference pooled normal human S9 (rHLS9-pooled)." (PMID 28634336, 2017).
cancer (2 papers, 2023 to 2025). A tumor composed of atypical neoplastic, often pleomorphic cells that invade other tissues. "The analysis revealed that, in comparison with normal tissues, a notable down-regulation of SULT1B1 was detected in ESCC cancer tissues." (PMID 41383582, 2025). "The results showed that compared to the paired normal tissues, ESCC cancer tissues demonstrated decreased SULT1B1 expression." (PMID 41383582, 2025). "The findings indicated that, in comparison with normal tissues, SULT1B1 was significantly down-regulated in ESCC cancer tissues." (PMID 41383582, 2025).
SULT1B1 also shares sentences with these, for which no sentence is quoted: colon cancer (1 paper); gastric cancer (1); metabolic disorders (1).